TERT (telomerase reverse transcriptase)
Diseases named in the same sentence as TERT in open-access papers (continued):
Sharing a sentence is not in itself a finding about the gene and the disease.
cancer (continued). "Mutations in the human telomerase reverse transcriptase (TERT) promoter are the most frequent non-coding mutations in cancer, but their molecular mechanism in tumorigenesis has not been established." (PMID 26194807, 2015). "The identification of the recurrent TERT and TAL1 mutations raises the possibility that other cis-regulatory regions may acquire somatic mutations that contribute to cancer by similar mechanisms." (PMID 26356674, 2015). "In summary, we developed a new HCC gene therapeutic strategy with high cancer-selectivity, the least targeting of normal cells, and efficient anticancer effects, based on the targeted replacement of TERT RNA through a trans-splicing ribozyme under control of liver-specific miR-122a expression." (PMID 26189916, 2015). "An extrapolation from topological analysis of the model suggests that TERT may be hard wired for transcriptional stability in cancer cells which has possible implications for pathway therapeutics approaches targeting telomerase." (PMID 24550717, 2014). "Recently, several genome-wide association studies (GWAS) reported that common polymorphisms of Telomerase reverse transcriptase-cleft lip and palate transmembrane 1 like, CLPTM1L (TERT-CLPTM1L), which is located at locus 5p15.33, were associated with the risk of many types of cancer." (PMID 25007268, 2014). "Both C228T and C250T mutations generate gain of function ETS1 binding motifs, and the mutant TERT promoter exhibits higher transcriptional activity than does its wild type counterpart in cancer cells, thereby contributing to cancer-specific telomerase activation." (PMID 24742867, 2014). "Moreover, TERT has been shown to induce epithelial-mesenchymal transition and a cancer stem cell phenotype, thereby promoting cancer metastasis and invasion." (PMID 24742867, 2014). "This may have potentially important implications for strategies targeting the expression of TERT in cancer cells since telomerase inhibition by targeting TERT activators may be more problematic than was previously thought." (PMID 24550717, 2014). "Recently, hotspot mutations in the TERT promoter namely C228T and C250T were identified in various human malignancies including urological tumors and the mutations create de novo ETS1 binding motifs, thereby facilitating TERT transcription and telomerase activation in cancer cells." (PMID 25474136, 2014). "In addition, TERT displays multiple activities independently of telomere lengthening and is capable of protecting cancer cells from apoptosis stimulated by various insults or stresses." (PMID 25474136, 2014). "More importantly, TERT could directly promote cancer cell invasion and metastasis by inducing epithelial-mesenchymal transition." (PMID 25474136, 2014). "However, many other factors bind the TERT promoter, co-operating with these and other pathways, and acting together to ensure telomerase expression in a wide variety of cancer cells." (PMID 24550717, 2014). "Our results suggest that the TERT gene is not wholly responsible for differences in lifespan and cancer susceptibility seen in dog breeds." (PMID 24423165, 2014). "Thus, how cancer-specific TERT expression is achieved has long been an important issue in cancer research, but remains incompletely understood." (PMID 25301727, 2014). "All Surv.m-CRAs induced potent in vitro and in vivo cytotoxic effects against a variety of malignant tumors, and exhibited stronger and more cancer-selective phenotypes than telomerase reverse transcriptase (Tert)-responsive m-CRAs (Tert.m-CRAs), which are currently among the best CRAs." (PMID 24467821, 2014). "However, it remains incompletely understood how the cancer-specific TERT transcription is activated." (PMID 24742867, 2014). "Suppressing telomerase is toxic to cancer cells and it is widely believed that understanding TERT regulation could lead to potential cancer therapies." (PMID 24550717, 2014).
cancer (continued). "Cancer cells depend on transcription of telomerase reverse transcriptase (TERT)." (PMID 24550717, 2014). "Clearly, TERT activation is common in human cancers and is likely oncogenic, but the mechanism of gene activation may differ between cancer types." (PMID 25159915, 2014). "The telomerase gene TERT is upregulated in multiple cancers." (PMID 25159915, 2014). "The candidate gene we chose to test this hypothesis was TERT, which controls self-renewal of normal and cancer stem cells, and whose expression is maintained by key leukaemic fusion oncogenes supporting its essential role in leukaemic propagation." (PMID 23229821, 2013). "Immortalized urothelial cells (TERT-NHUC), uncultured epithelial cells and cells from connective ureter tissue exhibited the same LINE-1 methylation levels found in urothelial cell cultures, whereas cancer-associated fibroblasts had comparably low methylation." (PMID 24133654, 2013). "Downregulation of TERT in telomerase-positive cancer cells results in growth arrest." (PMID 23946780, 2013). "Here we show that endogenous telomerase (TERT protein) shuttles from the nucleus into mitochondria upon oxidative stress in cancer cells and analyzed the nuclear exclusion patterns of endogenous telomerase after treatment with hydrogen peroxide in different cell lines." (PMID 23326372, 2013). "A better insight into the biological consequences of different subcellular localizations of TERT might lead to the development of more effective anti-cancer treatments." (PMID 23326372, 2013). "We hypothesize that the observed differences between cancer types may be attributable to differing degrees of cellular heterogeneity, or to differing degrees of TERT sensitivity." (PMID 24152305, 2013). "Moreover, the expression of TERT (catalytic subunit of telomerase), correlates with telomerase activity and upregulation of TERT expression plays a critical role in human carcinogenesis suggesting that TERT is a good target for cancer therapy." (PMID 23967300, 2013). "For TERT gene, we compared one pair of samples where the only the cancer tissue harbors the integration, another pair of samples where both the HCC and the adjacent tissues harbor the HBV integration, and 6 pairs of samples where none of the tissues harbor the HBV integration." (PMID 23236287, 2012). "Similarly, the NF-κB transcription factor also induces the zfTERT promoter, suggesting that the zebrafish is also a good model for studying the influence of inflammation on TERT expression and cancer development." (PMID 21347393, 2011). "Recently, the TERT MNS16A has been studied in many cancers, but the results are conflicting." (PMID 21929825, 2011). "Cancer incidence is higher among patients with TERC and TERT mutations, significantly so compared to the TINF2 group (P-value = 0.003 and 0.011, respectively); this may well reflect the fact that they are generally an older patient group." (PMID 21931702, 2011). "Indeed, studies have shown that TERT able to trigger antitumor cytotoxic T lymphocyte (CTL) responses, and immunization of mice with TERT stimulated TERT-specific CTL that can kill cancers of various origins." (PMID 20856939, 2010). "Together these findings suggest that the TERT-CLPTM1L 5p15.33 region could be important in the development of a spectrum of cancers." (PMID 20700438, 2010). "Dysregulation of TERT is thought to be a contributing factor in cancer development." (PMID 18366794, 2008). "However, in the future, if these specimens were found to carry such cancer-associated TERT and HRAS oncogenic variants, the diagnosis of noncancerous PVL for the tested samples should perhaps be re-considered." (PMID 41489678, 2026). "Additionally, numerous non-coding RNAs bind to TERT, including various microRNAs (miRNAs) that target the 3′-untranslated regions (3′-UTRs) and open reading frames of TERT, thereby modulating its expression in various cancer cell types." (PMID 41301813, 2025).
cancer (continued). "Additionally, mutations in TERT, the gene encoding telomerase reverse transcriptase, are found in a significant percentage of HCC cases, facilitating telomere maintenance and allowing cancer cells to evade replicative senescence." (PMID 40869967, 2025). "However, increase in TERT activity may lead to unrestricted self-renewal of cells, one of the hallmarks of cancer." (PMID 40307280, 2025). "TERT mRNA expression level has been investigated as a biomarker in addition to telomerase enzymatic activity since it has been shown to be the rate-limiting factor of telomerase activity in a number of cancers, including breast, non-small cell lung, and urothelial cancer." (PMID 40151802, 2025). "Additionally, studies have indicated that the atypical functions of TERT within cells may also contribute to its involvement in cancer, particularly through its roles in gene expression regulation and cell proliferation." (PMID 40362481, 2025). "While the expression of TERT has been primarily studied for its role in the context of cancer, our data suggest that it may also prime cells against specific stress responses, particularly when analyzing pathway enrichment for both DNA damage response and repair." (PMID 39975037, 2025). "Moreover, since the mitochondrion is considered a mediator of tumorigenesis and TERT is expressed in 85% of tumors, clarifying the mitochondrial TERT mechanism of action and its connection with mitochondrial functions will help better define the role of mitochondria in cancer." (PMID 41144538, 2025). "JUN may indirectly promote the expression of TERT, activate telomerase activity, compensate for telomere shortening during cell division, maintain chromosomal stability, and assist in the unlimited proliferation of cancer cells." (PMID 40666524, 2025). "Indeed, TERT, the catalytic subunit of telomerase, is ubiquitously expressed across cancer types." (PMID 39095874, 2024). "Thus, upregulation of TERT might promote the clonal expansion of cancer cells by activating the MYC pathway, in addition to maintaining telomere function." (PMID 39020172, 2024). "Additionally, CRISPR-Cas9-mediated TERT gene editing may sensitize cancer cells to other therapies, as telomerase inhibition can enhance the effectiveness of conventional treatments like chemotherapy or radiation therapy." (PMID 38195537, 2024). "They suggested that, for the majority of cancers, TERT reactivation may be entirely epigenetic." (PMID 39000438, 2024). "Additionally, researchers have developed a new class of potent telomerase inhibitors that may enhance the sensitivity of conventional cytotoxic cancer therapies by targeting TERT." (PMID 39131044, 2024). "A few single-nucleotide variants (SNVs) in TERT, RTEL1, and NAF1 genes are reported to associate with long telomeres, suggesting that they may be associated with an increased risk of cancer, as shown for rs2736100 in the TERT gene that is associated with an increased risk of adenocarcinoma." (PMID 38397754, 2024). "Furthermore, it contributes to TERT reactivation, promoting cancer incidence and progression." (PMID 39228402, 2024). "However, cancer cells are unique in that they could upregulate TERT expression to ensure telomere length increases after each cell division." (PMID 38538106, 2024). "Since the hotspot mutations in TERT promoter had been well accepted to create de novo binding sites for GABPA/GABPB complex, most of previous studies aiming at targeting mutant TERT in human cancers were focused on targeting GABPA and/or GABPB directly or indirectly." (PMID 38769666, 2024).
cancer (continued). "Hence, there were 100 carcinomas (29.4%) with neither RAS nor BRAF V600E or TERT promoter variants (eTable 1 in Supplement 1)." (PMID 38758552, 2024). "TERT via interaction with a variety of intracellular signaling pathways significantly increases cell survival, including genetically modified cells with TERT overexpression, and may increase the resistance of cancer cells to therapy." (PMID 37189709, 2023). "Furthermore, TERT promoter mutations cooperate with TPP1 promoter nucleotide changes to lengthen telomeres and with mutated BRAF and FGFR3 oncoproteins to enhance oncogenic signalling in cancer cells." (PMID 38033865, 2023). "From our results, we hypothesized the following combination algorithm: a decrease in cfDNA level, normal ERBB2 copy number, and absence of TERT C228T mutations after drug therapy indicate the suppression of cancer (PR)." (PMID 37945655, 2023). "We hypothesized that decreased cfDNA levels, a normal copy number of ERB-B2 receptor tyrosine kinase 2 (ERBB2), and the absence of the TERT C228T mutation indicate cancer suppression." (PMID 37945655, 2023). "Overall, our findings indicate that we may be able to decipher a regulated TERT AS code that controls telomerase in stem cells, and that cancer cells probably use several different codes to induce FL TERT and telomerase via alternative RNA splicing factor expression." (PMID 37531400, 2023). "Upon establishing haplotype analysis of TERT*(rs2736098 and rs2736100) variants, our team identified a perceptible association of TERT (rs2736098*A and rs2736100*T) haplotypes among HCC patients compared with cancer-free controls [24.5% vs. 14.8%, OR = 1.87, 95% CI = 1.17–2.98, p-value = 0.009]." (PMID 37884663, 2023). "In addition, of all the 31 Onco/TSGs harboured sHyperMethyl and sHypoMethyl in their gene body, 7 genes (HOXD11, TAL1, HOXA9, PAX5, FOXP1, FOXO1, TERT) were reported to serve as potential DNA methylation-based biomarkers for non-invasive early cancer diagnosis." (PMID 37393582, 2023). "The human TERT protein (hTERT) is the catalytic subunit of telomerase, an enzyme complex that is primarily responsible for maintaining telomere length and replication potency of stem cells; its activity is thought to be vital for the immortalization of cancer cells." (PMID 37511853, 2023). "Thus, inactivating TERT has become a promising means of cancer therapy." (PMID 36980699, 2023). "Finding conserved or different TERT AS regulation in multiple cell and tissue types will result in the identification of therapeutic approaches by which specific manipulation of telomerase activity can be achieved in certain cell types (e.g., cancer cells versus stem cells)." (PMID 37531400, 2023). "Additionally, TERT expression can be downregulated in cancer cells under IFNa treatment." (PMID 37189709, 2023). "In addition to TERT, BLCAP, and KBTBD8, we also observed low levels of damage induction in UV-irradiated melanocytes at a number of other recurrent mutations in the promoters of known or suspected cancer genes (i.e., TCF3, TOP2A, NUMB, FOSB, and OTUB2)." (PMID 37169747, 2023). "TERT gene, located in human chromosome 5p15.33, is the catalytic subunit of telomerase, is an indispensable and important part of telomerase-holoenzyme, and can play a crucial role in the formation of carcinoma through telomere-dependent or independent mechanism." (PMID 37664030, 2023).
cancer (continued). "Besides, a comprehensive research synopsis with systematic functional annotation had not been performed to evaluate the epidemiological evidence of genetic correlations between TERT and CLPTM1L genes and susceptibility to cancers or non-cancer disease until now." (PMID 35847915, 2022). "The mutant TERT promoter is transcriptionally active and contains the H3K4me2/3 active chromatin mark and recruits the GABPA/B1 transcription factor, whereas in several cancer cell lines, the wild-type allele retains the H3K27me3 epigenetic silencing mark and is transcriptionally inactive." (PMID 35326649, 2022). "TERT, as the catalytic component of telomerase, is not only required for infinite proliferation of cancer cells by stabilizing telomere length, but also operative in promoting invasion, metastasis and other cancer hallmarks via a telomere lengthening-independent function." (PMID 35549739, 2022). "Thus, the regulation of mitochondrial TERT to enhance mitochondrial biogenesis may contribute to the aberrant proliferation and survival of cancer cells." (PMID 35741087, 2022). "Moreover, with the recent development of high-throughput sequencing technology, the massive mapping of cancer genomic and epigenomic landscapes further identified genetic and epigenetic alterations to drive TERT transcription, such as aberrant TERT promoter methylation." (PMID 36713366, 2022). "It is not clear how serum starvation causes the decrease in TERT across cancer types." (PMID 36130485, 2022). "Besides, cancer cells can present TERT peptides via CD4+ or CD8+ T cells." (PMID 35903534, 2022). "However, the question remains whether a variation in TERT expression and LTL, possibly affected by DNA-damaging anticancer drugs, can be the biological mechanism underlying the inadequate response to cancer therapy." (PMID 36203452, 2022). "Interestingly, as in human cancer, expression of E6/E7 mRNA in 4T1luc2 induced expression of TERT." (PMID 35804391, 2022). "Therefore, if the role of reactivated TERT in cancer is not limited to telomere elongation, the question remains: how else could TERT contribute to cancer progression?" (PMID 33599797, 2021). "The next challenge will be integrating the multiple facets of TERT regulation and removing the ambiguity of isoform-level RNA sequencing while sustaining the large-scale feasibility necessary to uncover cell-type specific nuances and novel cancer therapeutic strategies." (PMID 33924498, 2021). "Thus, TERT plays an important role in oncogenesis and the immortality of cancer cells." (PMID 33946181, 2021). "Epigenetic manipulation of TERT could be a promising approach for the treatment of cancer." (PMID 33802026, 2021). "Furthermore, they also point to the importance of choosing the right strategy when using telomerase inhibitors against cancer, since it can be more important to inhibit the extracurricular role of TERT by physically preventing its binding to DNA than inhibiting its enzymatic activity." (PMID 33713376, 2021). "The nuclear localization and intron retention observed in healthy iPS cells that endogenously express TUG1 and TERT led us to explore whether this phenomenon also occurs in other cell types and contexts such as cancer, where TERT expression is reactivated and TUG1 is expressed." (PMID 34083519, 2021). "It was found that BRAF V600E, RET/PTC1 and TERT mutations were associated with aggressive characteristics, whereas BRAF K601E, HRAS, NRAS, KRAS, PAX8-PPARy mutations and tumors with no mutations are significantly less likely to be associated with high risk cancers." (PMID 33910629, 2021). "In a previous study, 22% of all TCGA cancers did not express TERT or had mutations in ATRX or DAXX." (PMID 34681758, 2021). "Thus, elucidation of TERT regulation of myofibroblast differentiation and senescence may provide insight into the basis for the difficulty in targeting fibroblasts in cancer therapy." (PMID 34253690, 2021).